CRP (C-reactive protein)
Diseases named in the same sentence as CRP in open-access papers (continued):
Sharing a sentence is not in itself a finding about the gene and the disease.
breast cancer (continued). "Body fat percentage, measured with Dual Energy X-ray Absorptiometer (DEXA), and circulating levels of CRP and SAA were obtained 30 months after breast cancer diagnosis." (PMID 22873489, 2012). "Therefore, other, larger studies are needed to answer unequivocally whether increased CRP levels at the time of diagnosis associate with recurrence of breast cancer or not." (PMID 21639875, 2011). "Although the age-adjusted HR for recurrence for the highest versus the lowest tertile of CRP was borderline significant, we did not detect a statistically significant association between elevated CRP levels and recurrence of breast cancer, which may suggest that no such association exists." (PMID 21639875, 2011). "In addition to NLR, other inflammatory markers, such as C-reactive protein (CRP), have been shown to play a critical role in evaluating breast cancer prognosis." (PMID 40141182, 2025). "C-reactive protein (CRP)-to-albumin ratio (CAR) is an inflammatory and nutritional biomarker that has been well studied and reported to have an impact on the survival of patients with diverse types of cancer, but limitedly in breast cancer." (PMID 40416620, 2025). "In this regard, we investigated these ten markers (EGFR2, CA15-3, CA27.29, MCA, CEA, CA125, CA19-9, CYFRA 21-1, ferritin, and CRP) in saliva with the aim of their possible use for the differential diagnosis of HER2-positive and HER2-negative subtypes of breast cancer." (PMID 40699615, 2025). "Thus, CYFRA 21-1 significantly increases with luminal A and luminal B(-), but CRP only increases with luminal A. CA15-3, CA27.29, MCA, and CA19-9 significantly decrease with luminal B(+) breast cancer." (PMID 40699615, 2025). "In addition, CA15-3, Type 1 T helper cells (Th1), C-reactive protein (CRP), and VEGF were also used in more than three studies for breast cancer for the purpose of diagnosis and treatment." (PMID 37181043, 2023). "In multi-state models, we further found that high CRP conferred greater risks for invasive breast cancer and its transition to breast cancer mortality rather than the transition from in-situ cancers to invasive cancers." (PMID 38000092, 2023). "Beyond CRP, the published data do not clearly support the role of inflammation in the development of breast cancer." (PMID 36867866, 2023). "Recent studies have reported the independent association between tumor relapse and elevation of serum inflammatory biomarkers, including C-reactive protein (CRP), interleukin-6, and serum amyloid A; this suggests that systemic inflammation affects breast cancer recurrence." (PMID 36473927, 2022). "Therefore, this meta-analysis will focus on the effects of exercise on IL-6, IL-10, IL-1β, CRP, TNF-α, IGF-1 and IGFBP-3 levels in breast cancer patients." (PMID 36482346, 2022). "Exercise reduces the postoperative levels of IGF-1, IL-6, CRP, IL-10 and TNF-α among patients with breast cancer, which may have a significant impact on inhibiting breast cancer recurrence and improving its prognosis." (PMID 36482346, 2022). "This is in line with the conceptual goals of Optimune, as regular aerobic exercise seems to reduce inflammatory markers, such as CRP, TNF-α, and Interleukin-6, and reducing chronic inflammation may improve the prognosis of breast cancer survivors." (PMID 33961667, 2021). "A test for synergy on the additive scale did not suggest a synergistic relationship between CRP and SAA in predicting increased risk of breast cancer relapse." (PMID 33483516, 2021). "In univariate Cox regression analysis, CRE, TBIL, LDH, UA, BUN, ALB, and CRP were correlated with the OS of breast cancer patients, while there is no statistical relationship between DBIL and OS." (PMID 34659642, 2021).
breast cancer (continued). "Future studies should involve more indicators, especially biomarkers such as leptins, C-reactive protein, and TNF-α, and should have expanded sample size and better study design to better reflect the effect of wearable technology intervention on breast cancer survivors." (PMID 33194634, 2020). "This study aimed to investigate cytokine mRNA expression levels of IL-6, IL-18, TNF-α, and CRP in hepatocytes from breast cancer xenograft mice with or without moderate exercise." (PMID 32309219, 2020). "BC: Breast Cancer, CRP: C - reactive protein, QoL: Quality of Life." (PMID 31759342, 2019). "High levels of CRP and cytokines (mainly IL6, IL1ß, and sTNF-RII) have been also reported in others studies among breast cancer survivors with cognitive impairment that suggested a dysregulation of the immune system as a possible mechanism of onset of cognitive decline." (PMID 31795208, 2019). "Finally, we used MRbase10 and further summary statistics for breast cancer (BCAC11) and C-reactive protein (CHARGE-CRP12) made available to us to perform two-sample Mendelian randomisation to investigate causal influences on lifespan." (PMID 29030599, 2017). "Nevertheless, our data indicated that increased preoperative CRP and PLR might represent an independent prognostic factor in patients with breast cancer." (PMID 28489884, 2017). "Breast cancer patients had the following means: 55.2 years age at diagnosis, BMI of 24.9 kg/m2, WHR of 0.88, % truncal fat of 37.3%, serum Triglycerides (TG) of 1.07 mmol/L and cholesterol of 5.61 mmmol/L, and a median serum CRP of 0.80 mg/L." (PMID 28649659, 2017). "Elevated CRP and serum amyloid A (SAA) were associated with reduced overall survival in women diagnosed with breast cancer, regardless of age, race, BMI and tumor stage." (PMID 27310615, 2016). "In addition to lung cancer, elevated levels of CRP and SAA have been observed in other types of cancer, including gastric cancer, esophageal squamous cell carcinoma, and breast cancer." (PMID 26264146, 2015). "Cumulative incidence of death due to breast cancer and recurrence was highest among women in high quarantine of CRP, but the incidence of recurrence was not increasing in a stepwise manner with rising levels of CRP." (PMID 26693355, 2015). "Based on large-scale gene expression analysis in a subgroup of 72 (48.6%) patients, we highlight for the first time, that circulating CRP is not related to the expression of genes in the corresponding carcinomas of the breast." (PMID 25340395, 2014). "The association between acute phase proteins and adiposity we found is consistent with earlier reports based on anthropometric measures that found increased adiposity was significantly correlated with elevated levels of CRP and SAA among breast cancer patients." (PMID 22873489, 2012). "Women who had gained more than 5% of their body weight since breast cancer diagnosis had non-statistically significant higher geometric mean levels of CRP and SAA." (PMID 22873489, 2012). "Moreover, inflammatory serum biomarkers, such as C-reactive protein (CRP) and serum ferritin, are elevated in breast cancer patients and correlate with advanced tumor stage and poor clinical outcome." (PMID 23300545, 2012). "Thus, it is possible that the present finding of an association between elevated CRP levels at the time of diagnosis of breast cancer and overall survival may not be breast cancer specific but can simply be due to CRP acting as a general marker of health and longevity." (PMID 21639875, 2011). "The cumulative incidence of recurrence among breast cancer patients was highest among women in the highest tertile of CRP, but the incidence of recurrence did not increase stepwise with increasing levels of CRP (log-rank trend, P = 0.24)." (PMID 21639875, 2011). "CRP estimation does not seem to be very useful in evaluating the patient with breast cancer, though its level correlates with that of IL-6." (PMID 21294915, 2011).
breast cancer (continued). "In the present study, albumin but not C-reactive protein was a significant, stage independent, predictor of survival in patients with primary operable breast cancer." (PMID 17375036, 2007). "Mean CRP level did not relate to changes in weight or body fat or FFM in patients with breast cancer or melanoma." (PMID 15726121, 2005). "Systemic inflammatory markers such as C-reactive protein (CRP), neutrophil-to-lymphocyte ratio (NLR), monocyte-to-lymphocyte ratio (MLR), and platelet-to-lymphocyte ratio (PLR) have been identified as potential prognostic and predictive indicators in various malignancies, including breast cancer." (PMID 40901118, 2025). "Moreover, it is noteworthy to mention that exercise intensity appears to have an important role in the regulation of cancer-related inflammation, as high-intensity exercise has been shown to lead to milder increases in C-reactive protein (CRP) and TNF-α in the plasma of breast cancer patients." (PMID 38136400, 2023). "In agreement with the majority of these studies, in our cohort of breast cancer survivors on AIs, depressive symptoms were significantly and positively correlated with CRP and IL-6 with similar, albeit non-significant patterns of associations noted for anxiety and perceived stress." (PMID 36717689, 2023). "Higher InCRP levels in WHEL participants were significantly associated with an increased risk for additional breast cancer events (HR 1.13, 95% CI 1.03–1.24, p = 0.03, model 3), while the DIANA-2 trial did not observe associations between CRP levels and recurrence." (PMID 36401194, 2022). "However, the combination of CEA and CA153 measurement does not possess satisfactory sensitivity in detecting metastasis of breast cancer, and the additional measurement of CA125, C-reactive protein (CRP), and other related biomarkers can improve the sensitivity of monitoring tumor progression." (PMID 35480092, 2022). "It has been demonstrated that coupling of S1P to S1PR3 can induce CRP expression via CCAAT/enhancer-binding protein β (C/EBPβ), activate Rac1/Nox-4/ROS/ERK pathways, and upregulate MMP9 activity, contributing to the aggressiveness and invasion of breast cancer." (PMID 34820423, 2021). "In addition, all of the biochemical parameters we analysed were statistically significant in both breast cancer patients (NF-κB: p<0.001; sTRAIL: p<0.01; TNF-α: p<0.001; IL-6: p<0.001; PCT: p<0.001; PTX-3: p<0.001; CRP: p<0.001) and colon cancer patients (for all p<0.001) compared to the control." (PMID 33776564, 2021). "Furthermore, The Alberta Physical Activity and Breast Cancer Prevention Trial found that TT, E2, and FE2 were significantly positively associated with CRP in postmenopausal women without hormone therapy." (PMID 35002960, 2021). "Recently, it has been reported that C-reactive protein (CRP) induced upregulation of ITGA2 and matrix metalloproteinase-9 (MMP-9) expressions by activating focal adhesion kinase, pilin, and ERK signal pathway, thus promoting the invasion of breast cancer cells." (PMID 32904605, 2020). "On multivariate analysis, CRP (hazard ratio [HR]: 2.85, 95% confidence interval [CI]: 1.03–7.88, P<0.05), PLR (HR: 2.61, 95% CI: 1.07–6.36, P<0.05) and nuclear grade (HR: 3.066, 95% CI: 1.26–7.49, P<0.05) were significant prognostic indicators of DFS in patients with breast cancer." (PMID 28489884, 2017). "It thus may not be surprising that patients have elevated CRP levels during treatment for breast cancer, when estrogen levels fall significantly." (PMID 26126656, 2015). "Results from subgroup analyses stratified by source of menstrual status showed that the elevated levels of CRP could increase the postmenopausal breast cancer, not the premenopausal breast cancer." (PMID 26001129, 2015).
breast cancer (continued). "Fatigue in breast cancer survivors has also been shown to correlate positively with peripheral CRP levels and leukocyte counts but not with IL1-receptor antagonist (RA), IL-6, and soluble TNF-Receptor1 (sTNF-R1), which again diminishes the role of a cytokine-specific mechanism." (PMID 25954147, 2015). "Further large-scale prospective investigations will be necessary in order to validate the effect of systemic inflammation on breast cancer prognosis as well as the potential clinical implementation of pre-operative CRP level as a prognostic biomarker in node-negative breast cancer." (PMID 25340395, 2014). "Data revealed that breast cancer subjects had significantly higher systolic blood pressure (p = 0.03), glucose (p = 0.01), triglycerides (p = 0.001), leptin (p = 0.044), resistin (p = 0.04), Ang II (p = 0.02), TNF-α (p = 0.045), and CRP (p = 0.04) than controls." (PMID 23374911, 2013). "A few days in the diagnosis, breast cancer subjects had significantly higher systolic blood pressure (p = 0.03), glucose (p = 0.01), triglycerides (p = 0.001), leptin (p = 0.044), resistin (p = 0.04), ANG II (p = 0.02), TNF-α (p = 0.045), and CRP (p = 0.04) than the controls." (PMID 23374911, 2013). "In conclusion, this study demonstrates that elevation in the serum inflammatory biomarkers CRP or SAA drawn randomly during treatment in the adjuvant setting are significantly and independently associated with increased risk of relapsed HR+/HER2− breast cancer, but not HR+/HER2+ breast cancer." (PMID 33483516, 2021). "In addition, since we lacked information on CRP or IL-6, further studies with these markers may shed light in the LIPG-breast cancer association." (PMID 34001944, 2021). "In addition, the combined OR per natural log unit change in CRP for breast cancer was not significantly affected by omission of any of the 15 individual studies, as well as no publication bias was observed in our analyses, indicating that our results were robust." (PMID 26001129, 2015). "Among premenopausal AA women, comparing variant allele carriers to non-carriers, reduced breast cancer risk was associated with CXCL5-rs425535 (OR=0.61, P=0.02), while among EA women, there were associations with TNFA-rs1799724 (OR =2.31, P =0.002) and CRP-rs1205 (OR=0.54, P=0.01)." (PMID 23991131, 2013). "For instance, integrating CRP and NLR values with imaging techniques has been shown to enhance sensitivity and specificity in detecting breast cancer, particularly in patients with non-palpable tumors." (PMID 40901118, 2025). "For instance, a study on dogs with mammary tumors showed significantly increased CRP and SAA during metastatic dissemination, although CRP levels did not correlate with prognostic factors." (PMID 40559770, 2025). "In a molecular mechanism study exploring the link between sleep and breast cancer, a positive correlation was identified between TGF-β and CRP levels and insomnia, while IL-6 showed a negative correlation with sleep-inducing medications." (PMID 38919616, 2024). "Recently, Lymphocyte to C-reactive Protein Ratio (LCR) has been reported to be related to cancer prognosis, but there is no relevant report on the relationship between LCR and breast cancer prognosis." (PMID 36922570, 2023). "Another study of 42 breast cancer patients treated with trastuzumab failed to predict CTRCD using TnT, C-reactive protein (CRP) and BNP measurements." (PMID 34859069, 2021). "Among a cohort of 2910 Danish women with breast cancer, OS and DFS were less in subjects with high CRP levels irrespective of the presence of distant metastasis and hormone receptor status." (PMID 26693355, 2015). "Also, lifetime exposure to elevated CRP levels is likely to influence the development of hormone receptor–positive and HER2/neu-negative breast cancer." (PMID 33614510, 2020).
breast cancer (continued). "Furthermore, other parameters that can be investigated using blood tests have not been evaluated, including C-reactive protein (CRP), lactate dehydrogenase (LDH), and albumin (Alb), which have been reported as prognostic predictors not only in breast cancer, but also in other types of cancer." (PMID 38965074, 2025). "CRP and SAA are nonspecific, acute-phase hepatic proteins secreted in response to cytokines, providing indirect evidence that cytokines may be contributing to breast cancer recurrence." (PMID 35136076, 2022).
acute kidney injury (336 papers, 2006 to 2026). Sudden and sustained deterioration of the kidney function characterized by decreased glomerular filtration rate, increased serum creatinine or oliguria. "The association between low expression levels of this module with acute kidney injury, and with high levels of CRP, leukocytes is likely reflective of the same association with disease severity." (PMID 38865072, 2025). "High expression of the turquoise module also associated with acute kidney injury, hypotension and high CRP and leukocyte counts." (PMID 38865072, 2025). "In this present case, the organ most affected was the kidney, with a severe form of renal failure, associated with severe systemic inflammation, as witnessed by the increase in C reactive protein, the main acute phase protein in dogs." (PMID 39728812, 2024). "Glycemia variation was associated with a higher risk of acute kidney injury in bacterial infection, while CRP levels at admission were associated with higher mortality in bacterial infection." (PMID 39768755, 2024). "One study demonstrated the strong association between elevated baseline CRP and the development of venous thromboembolism, acute kidney injury, critical illness, and even mortality." (PMID 38766546, 2024). "The emerging literature data reveal that serum CRP levels act as a risk factor for acute kidney injury (AKI), in which it can be increased, and it seems to be positively correlated with AKI severity." (PMID 37873776, 2023). "Given the association found with the CRP as an indicator of the inflammatory response, clinical significance of Cu/Zn ratio for treatment outcome and further progression of renal failure is evident in our study population." (PMID 34631763, 2021). "Vitamin C reduces sequential organ failure assessment score, C-reactive protein and procalcitonin, and prevents colistin associated acute kidney injury." (PMID 33324236, 2020). "Previously we established that human C-reactive protein (CRP) exacerbates mouse acute kidney injury and that the effect was associated with heightened renal accumulation of myeloid derived cells with suppressor functions (MDSC)." (PMID 31620123, 2019). "A high sensitivity C-reactive protein to albumin ratio (hs-CRP/Alb) predicts mortality risk in patients with acute kidney injury." (PMID 25793462, 2015). "A prospective study in Italy showed that statin use did not affect critical care admission and mortality but significantly lowered the risk of developing acute kidney injury (OR 0.47, 95% CI 0.23–0.95; p = 0.036) and C-reactive protein (CRP) levels (p = 0.048)." (PMID 40137827, 2025). "Inflammatory markers such as CRP, IL-6 and IL-18 have been linked to organ failure and could be indicators of acute kidney injury." (PMID 39563441, 2024). "Meanwhile, many factors caused by renal failure, such as high blood calcium, phosphorus and lipids, C-reactive protein (CRP), and serum creatinine (Scr), may affect the patency of AVF." (PMID 36836441, 2023). "Blood analysis showed an inflammatory response with CRP at 211 mg/L and a leukocyte count of 17,000/mm3 with a predominance of neutrophils, associated with acute renal failure (creatinine level of 200 μmol/L with an estimated clearance of 29 mL/min and blood urea nitrogen at 20.1 mmol/L)." (PMID 29326675, 2017). "CRP is a risk factor for acute kidney injury (AKI) and CKD by leading to the decline of the estimated glomerular filtration rate (eGFR)." (PMID 38685954, 2024). "Independent risk factors for mild pelviectasis were hyponatremia, CRP > 80 mg/L, and acute kidney injury (AKI) at the moment of febrile UTI diagnosis." (PMID 37587378, 2023). "Case fatality rate, the requirement of invasive mechanical ventilation (IMV), and acute kidney injury (AKI) were associated with previous fasting blood glucose, and C-reactive protein (CRP), and lactate dehydrogenase (LDH) levels on admission." (PMID 35957939, 2022).